MOG (myelin oligodendrocyte glycoprotein)
Diseases named in the same sentence as MOG in open-access papers (continued):
Sharing a sentence is not in itself a finding about the gene and the disease.
multiple sclerosis (continued). "In a similar manner, the MOG peptide model of EAE is widely used to assess drug candidates for multiple sclerosis and serves as a mechanistic model for activation and expansion of self-reactive T cells (Th1, Th17) that induce and propagate injury to the spinal cord of mice." (PMID 35790728, 2022). "Even though testing serum MOG antibody IgG made the distinguishment of MOG-AD from typical multiple sclerosis (MS) or other common forms of neuroinflammation more specific and faster, the role of MOG antibody IgG in MOG-AD remains unclear." (PMID 36313865, 2022). "however, found no “increase in the risk of clinically definite multiple sclerosis or of multiple sclerosis according to the McDonald criteria among patients who were positive for anti-MOG antibodies, anti-MBP antibodies, or both”." (PMID 34889995, 2022). "Multiple sclerosis (MS) disease is another CNS disease, and studies have provided evidence that myelin oligodendrocyte glycoprotein (MOG) specific antibodies and T-cells might contribute to MS." (PMID 36408389, 2022). "MOG may be used as a diagnostic marker and possible target in diseases including ADEM, MDEM, and rarely multiple sclerosis in which IgG1 antibody production against MOG is found." (PMID 36289819, 2022). "The available literature delineating imaging features of spinal cord lesions in children with multiple sclerosis (MS) and other acquired demyelinating diseases largely predates the availability of testing for antibodies to myelin oligodendrocyte glycoprotein (MOG)." (PMID 34643718, 2021). "In a mouse model of multiple sclerosis, AAV encoding the full myelin oligodendrocyte glycoprotein could mitigate the induction and severity of the disease." (PMID 34521922, 2021). "One of our “clinically definite multiple sclerosis” cases was found to be MOG-antibody positive." (PMID 33510701, 2020). "Therefore, we compared AQP4 and MOG specific peripheral T-cell response in individuals with AQP4-Ab (n = 8), MOG-Ab (n = 10), multiple sclerosis (MS, n = 8), and healthy controls (HC, n = 14)." (PMID 32625206, 2020). "The presented study involves the investigation of deaminated products in combination with experimental autoimmune encephalomyelitis (EAE, animal model of multiple sclerosis (MS)), the evaluation of 35–55 myelin oligodendrocyte glycoprotein (MOG35–55) epitope that contains the -Asn53-Gly54- sequence." (PMID 33066323, 2020). "When studying the functional role of multiple sclerosis risk genes and pathways during disease onset and their interactions with the environment, spontaneous OSE may thus show advantages over MOG-induced EAE." (PMID 33072080, 2020). "One multiple sclerosis (MS) control serum was MOG seropositive." (PMID 33510701, 2020). "If this is indeed the case and the MOG-induced EAE resembles human multiple sclerosis (MS) in pathogenesis, then the FcμR EM41-42QL mutant offers an intervention in individuals with MS, using gene editing that permits reliable introduction of point mutations in induced pluripotent human stem cells." (PMID 33584711, 2020). "We have thus used gene expression profiling to study whether spontaneous opticospinal EAE (OSE) or MOG-induced EAE mirrors the genetic contribution to the pathogenesis of multiple sclerosis more faithfully." (PMID 33072080, 2020). "Olsen and collaborators hypothesized that the MOG gene might have a specific methylation pattern in oligodendrocytes and might represent a way to assess disease activity in multiple sclerosis." (PMID 32813850, 2020). "The best classifiers between MOG antibody disease and multiple sclerosis were similar in adults and children, and included ovoid lesions adjacent to the body of lateral ventricles, Dawson’s fingers T1 hypointense lesions (multiple sclerosis), fluffy lesions and three lesions or less (MOG antibody)." (PMID 31212763, 2019).
multiple sclerosis (continued). "While the clinical relevance of MOG Ab detection is becoming increasingly clear as therapeutic and prognostic differences from multiple sclerosis are acknowledged, an in-depth characterization of human MOG Ab is required to answer key challenges in patient diagnosis, treatment, and prognosis." (PMID 31481127, 2019). "Cell-based assays for MOG-IgG were rarely positive in multiple sclerosis or NMOSD-AQP4-IgG." (PMID 30382857, 2018). "MOG-IgG-related encephalomyelitis (MOG-EM) is now considered by many experts a disease entity in its own right, pathogenetically distinct from both classic multiple sclerosis (MS) and aquaporin-4 (AQP4)-IgG-positive neuromyelitis optic spectrum disorders." (PMID 29554927, 2018). "Since partial Sgpl1 deficiency appears to phenocopy the effect of FTY720 on T cell distribution, we asked if it would also confer protection in murine MOG-induced EAE, a model of multiple sclerosis that depends on the infiltration of pathogenic T cells into the brain." (PMID 23544080, 2013). "The concomitant pharmacological down-regulation of the MyD88 signaling pathway was neuroprotective in vivo and attenuated inflammatory responses in the myelin oligodendrocyte glycoprotein (MOG) peptide induced experimental allergic encephalitis (EAE) model of multiple sclerosis (MS)." (PMID 23029281, 2012). "Multiple sclerosis (MS) is associated with pathogenic autoimmunity primarily focused on major CNS-myelin target antigens including myelin basic protein (MBP), proteolipidprotein (PLP), myelin oligodendrocyte protein (MOG)." (PMID 22316121, 2012). "Myelin/oligodendrocyte glycoprotein (MOG) is a putative autoantigen in multiple sclerosis (MS)." (PMID 22093619, 2011). "Our findings highlight myelin oligodendrocyte glycoprotein splicing as a factor that could be critical to the phenotypic expression of multiple sclerosis." (PMID 17573820, 2007). "Although myelin oligodendrocyte glycoprotein is a candidate autoantigen in multiple sclerosis, its function remains unknown." (PMID 17573820, 2007). "In patients with multiple sclerosis, the results of an MOG antibody titer may be falsely positive." (PMID 38921263, 2024). "ON can be the initial event in multiple sclerosis (MS), including clinically isolated syndrome (CIS), in aquaporin-4-IgG positive (AQP4-IgG+) and seronegative neuromyelitis optica spectrum disorders (NMOSD), and in myelin oligodendrocyte glycoprotein-IgG (MOG-IgG+)-associated disease (MOGAD)." (PMID 36908609, 2023). "Finally, the genetic susceptibility of the NMO group negative for AQP4-Ab needs to be analyzed with caution because optic spinal disease could be related to Asian type MS, Conventional Multiple Sclerosis, or MOG-IgG related disorders." (PMID 33420337, 2021). "In fact, 50 % of the MOG-IgG-positive patients in this study had clinical or radiological involvement of the brain in addition to ON and/or myelitis and the Barkhof and McDonald criteria for multiple sclerosis (MS) were met by 15 % and 33 %, respectively, as shown in parts 2 and 3 of this series." (PMID 27788675, 2016). "An example of the use of this approach is biodegradable PLGA nanoparticles loaded with myelin oligodendrocyte glycoprotein (MOG) peptides, which has shown efficacy in models of multiple sclerosis mediated by immune tolerance." (PMID 41465368, 2025). "Preliminary data indicate myelin oligodendrocyte glycoprotein (MOG)-CAR-Tregs secrete remyelination-promoting factors, positioning them as a potential therapeutic approach for multiple sclerosis (MS) where neuroprotection is paramount." (PMID 41050649, 2025). "MOG antibody disease (MOG-AD) is a monophasic or relapsing inflammatory demyelinating disease of the CNS associated with the presence of immunoglobulin G (IgG) antibodies against MOG which does not meet the criteria for multiple sclerosis or other neuroinflammatory disorders." (PMID 38975430, 2024).
multiple sclerosis (continued). "MOGAD is characterized by the presence of antibodies against myelin oligodendrocyte glycoprotein (MOG), distinct from those seen in multiple sclerosis (MS)." (PMID 39156322, 2024). "MOG and MBP peptides are used in EAE induction because multiple sclerosis patients have high levels of anti-MOG and anti-MBP antibodies, justifying the use of these factors for EAE induction in animal models." (PMID 39000105, 2024). "A similar mechanism of inflammatory demyelination involving different components of endoplasmic reticulum stress has been proposed for demyelination in both the MOG + IFA rat EAE model and in multiple sclerosis." (PMID 38426111, 2024). "Multiple sclerosis (MS), neuromyelitis optica (NMO) and myelin oligodendrocyte glycoprotein antibody disease (MOGAD) are inflammatory diseases of the central nervous system (CNS) with a multifactorial aetiology." (PMID 37374092, 2023). "Multiple sclerosis, NMO, myelin oligodendrocyte glycoprotein (MOG) antibody disease, and other demyelinating diseases are frequently associated with ON." (PMID 37033552, 2023). "Comparison of MOG-specific CD8+ T cells and memory T cell subsets in peripheral blood between patients with multiple sclerosis (MS), other neurological disease (OND) and healthy controls (HC)." (PMID 37215118, 2023). "It has not been suggested that in case of typical clinical or radiological manifestation of multiple sclerosis, clinicians need to perform testing for AQP4−Ab or MOG-Ab." (PMID 35884693, 2022). "Multiple sclerosis (MS) and acute disseminated encephalomyelitis (ADEM) have also been reported, as well as more rarely, myelin oligodendrocyte glycoprotein (MOG) antibody LETM." (PMID 35399911, 2022). "TDL can emerge not only as part of the spectrum of classic multiple sclerosis (MS) but also can represent an idiopathic monophasic disease, a relapsing disease with recurrent TDL, or could be part of the myelin oligodendrocyte glycoprotein (MOG)- and aquaporin-4 (AQP4)-associated disease." (PMID 35418930, 2022). "Herein, we present a case with recurrent episodes of short-segment myelitis typical for multiple sclerosis, but later diagnosed as MOGAD by MOG antibody seropositivity." (PMID 34220818, 2021). "They transplanted human iNSCs into the brain of mice with experimental autoimmune myelin oligodendrocyte glycoprotein (MOG)‐induced encephalomyelitis (EAE), a mouse model of multiple sclerosis (MS)." (PMID 31663609, 2019). "Patients with MOG-IgG often have bilateral, ill-defined, and large brain lesions, often with deep grey matter involvement, unlike classic multiple sclerosis lesions." (PMID 40547008, 2025). "Recently, a novel low-dose MOG + IFA–induced EAE rat model was introduced in DA and SD rats to investigate pain with minimal motor impairment/disability and to find a potential treatment for multiple sclerosis–related pain." (PMID 38426111, 2024). "Myelin oligodendrocyte glycoprotein (MOG) is a crucial component of the myelin sheath within the central nervous system (CNS) and plays a significant role in autoimmune diseases such as multiple sclerosis (MS)." (PMID 39518908, 2024). "In the present study, we showed alterations of the glutamate transporter EAAT5 in the mouse model of multiple sclerosis and demonstrated that the EAAT5 glutamate transporter is less enriched at photoreceptor synapses of MOG/CFA-injected EAE mice in comparison to CFA-injected control mice." (PMID 39595111, 2024). "Expression of the myelin oligodendrocyte glycoprotein (MOG) gene, a target antigen for myelin-destructive antibodies in autoimmune CNS demyelinating diseases, such as multiple sclerosis, and a cell surface marker of oligodendrocyte maturation, was also significantly decreased in schizophrenia." (PMID 38694089, 2024).
multiple sclerosis (continued). "Various forms of this disease, namely optic neuritis-related neuromyelitis optica spectrum disorder (NMOSD-ON), myelin oligodendrocyte glycoprotein (MOG-ON), multiple sclerosis (MS-ON) and double seronegative optic neuritis (DN-ON), with distinct clinical characteristics." (PMID 36977296, 2023). "In the last decades, Abs targeting the MOG protein and the water channel AQP4 have been identified in patients with inflammatory demyelinating disorders, defining clinically and immunologically distinct diseases from multiple sclerosis." (PMID 34997443, 2022). "Other studies demonstrated that MRI brain lesion distribution criteria may help to distinguish MOG-IgG+ and AQP4-IgG+ patients from multiple sclerosis patients." (PMID 33101166, 2020). "Additionally, studies have shown a link between multiple sclerosis and the existing HBV vaccine, with the mechanism relying on the amino acid similarity between HBsAg and the myelin oligodendrocyte glycoprotein (MOG) or other myelin antigens." (PMID 33042118, 2020). "The concept of epitope spreading has been reported in multiple sclerosis, AQP4 Ab in NMO, but not in MuSK Ab-associated myasthenia gravis, nor in 11 paediatric MOG Ab responses." (PMID 31481127, 2019). "Myelin oligodendrocyte glycoprotein (MOG) is an antigen of the myelin sheath, which may trigger immune cell responses and the production of auto‐antibodies in multiple sclerosis (MS)." (PMID 26493273, 2016). "The therapeutic potential of plant miRNAs was confirmed in a mouse model of human multiple sclerosis, EAE induced by active MOG immunization, where intravenous injections of 1.5 μg of DOTAP-complexed plant sRNA extracts significantly attenuate the pathology development of EAE." (PMID 27167363, 2016). "MOG-IgG has been reported in other non-NMO diseases including multiple sclerosis, acute disseminated encephalomyelitis and even some normal subjects." (PMID 24685353, 2014). "A couple of weeks later, we received results from LP; multiple sclerosis, acute demyelinating neuropathy, and myelin oligodendrocyte glycoprotein (MOG) disease were ruled out, as both oligoclonal bands, ganglioside antibodies, and anti-MOG were negative in the cerebrospinal fluid (CSF)." (PMID 40772147, 2025). "Myelin oligodendrocyte glycoprotein antibody disease (MOG-AD) is characterized by its monophasic or relapsing course and inflammatory demyelinating condition which is unable to be classified in typical multiple sclerosis (MS) or other known neuroinflammatory conditions." (PMID 36313865, 2022). "Unlike MOGAD, multiple sclerosis (MS) patients do not have MOG-Abs." (PMID 34220827, 2021). "PON has a high impact on the quality of life as it may or may not evolve into other acquired demyelinating syndromes (ADSs), such as multiple sclerosis (MS), neuromyelitis optica (NMO), or other syndromes related to the myelin oligodendrocyte glycoprotein IgG antibodies (MOG-IgG)." (PMID 34682120, 2021). "We enrolled 49 NMOSD patients [25 aquaporin-4 antibody (AQP4-Ab)–positive, 8 myelin-oligodendrocyte glycoprotein antibody (MOG-Ab)-positive, and 16 seronegative patients], 12 multiple sclerosis (MS) patients, and 15 other noninflammatory neurological diseases (OND) patients." (PMID 30426010, 2018). "For example, the assay used here, which employs C-terminal truncated rather than full-length MOG, did not detect MOG-IgG in adult multiple sclerosis patients and normal individuals, which suggests that different assays detect different subpopulations of MOG-IgG." (PMID 24685353, 2014). "Until recently, it was speculated that MOG could be a potential autoantigen in multiple sclerosis (MS); however, this is not the case, as neuroinflammatory disease associated with MOG antibodies has a different clinical phenotype from MS with a range of manifestations." (PMID 38804311, 2024).
multiple sclerosis (continued). "Fatigue is a common and disabling symptom amongst people with multiple sclerosis, however it has not been compared across the central nervous system (CNS) inflammatory diseases associated with aquaporin‐4 (AQP4) and myelin oligodendrocyte glycoprotein (MOG) antibodies (Ab)." (PMID 32187851, 2020). "In multiple sclerosis “mimics”—NMOSD and MOGAD—especially in the individuals that are seronegative for the specific autoantibodies (AQP4 and MOG-Ab), according to researchers, NfL levels do not represent a useful tool in the differential diagnosis." (PMID 40362691, 2025). "In two additional patients negative for both MOG and AQP-4 antibodies, ataxia was sensory and explained by cervical myelitis as part of multiple sclerosis (MS) manifesting temporal relation to NMDAR-E." (PMID 39735552, 2024). "For example, a peptide approach identified epitopes in myelin oligodendrocyte glycoprotein (MOG) and myelin basic protein (MBP) in patients with multiple sclerosis proteins, but these proteins were not identified using the Human ProtoArray." (PMID 36690876, 2023). "In our present study we show that autoimmunity in one of these cases is directed against MOG, and that the diagnosis in this case is MOGAD and not multiple sclerosis." (PMID 33242149, 2021). "A 15-year old boy with multiple sclerosis (MS) harbored NMDAR antibodies in CSF at 1:12 (serum negative) < 1 month after the first disease signs; myelin oligodendrocyte glycoprotein (MOG) and aquaporin-4 (AQP4) antibodies were negative." (PMID 32246252, 2020). "Previous studies suggest that children with MOG-abs rarely have an OCB in contrast to children with multiple sclerosis (MS); however, our study showed a higher OCB rate in children with MOG-abs (2/8, 25%) than in children without MOG-abs (0/7, 0%)." (PMID 33329345, 2020). "Multiple sclerosis was discriminated from MOG antibody disease and from AQP4 antibody disease with high predictive values, while MOG antibody disease could not be accurately discriminated from AQP4 antibody disease." (PMID 31212763, 2019). "Myelin oligodendrocytes glycoprotein (MOG) antibody-associated disease (MOGAD) represent 25% of pediatric acquired demyelinating syndrome (ADS); 40% of them may relapse, mimicking multiple sclerosis (MS), a recurrent and neurodegenerative ADS, which is MOG-Abs negative." (PMID 34220827, 2021). "Similarly, in an EAE model mice used to study multiple sclerosis in humans, the IL-1R was found to be required for induction of EAE by active immunization with the antigen MOG but not for induction of EAE induced by transfer of MOG-specific T cells." (PMID 26394985, 2015).